MIR4673 (microRNA 4673)
Synonyms: hsa-mir-4673
Gene: MicroRNA gene on chromosome 9 (136,519,568 to 136,519,626, reverse strand). Ensembl gene ENSG00000263403.
Homologues: Orthologues: chimpanzee MIR4673 (100% identical).